CD4 (CD4 molecule)
Diseases named in the same sentence as CD4 in open-access papers (continued):
Sharing a sentence is not in itself a finding about the gene and the disease.
infection (continued). "Altogether, our new data indicate that depletion of CD4+ T-cells prior to SIV infection results in activation of monocyte and massive infection of tissue-resident macrophages, which appear to be the predominant population of productively infected cells." (PMID 25356757, 2014). "To evaluate the impact of CD4, CXCR4 and CCR5 decreased expression in HIV-1 de novo infection, we treated human PBMC isolated from three donors with different concentrations of ING-B for 24 h." (PMID 24827152, 2014). "In the 10NOS2−/− FP, there was a significantly stronger IFN-γ response to the crude antigens and ML2028 (Ag85B), as well as to ML0380 (GroES), ML2038 (bactoferritin), and ML1877 (EF-Tu) by both CD4+ and especially CD8+ T cells at the site of infection." (PMID 25210773, 2014). "Following infection, an increase in the proportion of MLNC Foxp3+CD4+ cells within the transferred Fox.DO11.10 population occurred in both strains to a similar extent." (PMID 24185641, 2014). "IL-12 plays roles in both the innate and adaptive immune responses through JAK-STAT signaling, leading to effector Th1 cell differentiation and IFN-γ production by CD4+, NK, and NKT cells in the initial stages of infection." (PMID 24795730, 2014). "We show that immunization with CJ2-gD2 elicits significantly greater HSV-2-specific CD4+ and CD8+ T-cell responses in the immunized mice compared with the sham-immunized control animals after infection with wild-type HSV-2." (PMID 24979708, 2014). "In contrast, B cells, and CD4 and CD8 T lymphocyte numbers increased with significantly elevated numbers at 72 hours post infection [B cells P<0.01, CD4 P<0.01, CD8 P<0.05] with CD4 cells being the predominant T cell type." (PMID 24847941, 2014). "Following infection with Listeria monocytogenes expressing 2W1S peptide, OX40 was briefly expressed by the responding 2W1S-specific CD4+ T cells, but only on a subset that co-expressed effector cell markers." (PMID 24771127, 2014). "Since it is not possible to associate any specific cytokine profile with protection against active TB, recent studies have tried to find a correlation between functional signatures of CD4 or CD8 T cells and the state of infection/disease." (PMID 24795723, 2014). "In particular, lower proviral DNA loads in MHC class IA M4 macaques and lower CD4+T cell counts in MHC class IA, IB, and class II M4 animals were detected during the acute and chronic phases of infection, respectively." (PMID 25356594, 2014). "The recombinant BCG was shown to enhance the control of infection, inducing total memory (CD44+) CD4+ and CD8+ T cells, and to potentiate the production of IFN-γ by both CD4 and CD8 T cells." (PMID 24795730, 2014). "CD4+ T cells, the primary cellular target of HIV-1, are progressively depleted during the course of infection, in a process by which the virus takes over the host cell machinery to successfully replicate." (PMID 25462981, 2014). "On week 9 after infection, significant differences between treatments in the total frequencies of TNF-α (p = 0.0077) and IL-2-producing-CD4+ T cells of the spleens (p = 0.0035) were found." (PMID 24966857, 2014). "To explore the possibility that the onset of neurologic disease is dependent on immune-mediated pathology, we depleted mice of CD4+ and CD8+ T cells prior to ΔNSs IN infection." (PMID 24922480, 2014). "Infection with C. rodentium induced a significant increase in the number of lamina propria CD3+ T cells, CD4+ T cells, CD8+ T cells, DC and macrophages at day 15 p.i. in wild-type mice." (PMID 25243744, 2014). "Both CD4+ and CD8+ T cells are sufficient to resolve an LVS primary infection, as mice depleted of either population individually clear the bacteria from the tissues." (PMID 24400128, 2014). "Cigarette smoke exposed mice displayed significantly less number of macrophages, neutrophils, CD4+ T cells and CD8+ T cells than the control mice on day 9 after H9N2 infection." (PMID 24465940, 2014).
infection (continued). "At the erythrocytic stage of infection, IFN-γ production by CD4+ T-cells and CD4+ T-cell help for the B-cell response are required for control and elimination of infected red blood cells." (PMID 25628621, 2014). "Strong HCV-specific CD4+ T-cell and CD8+ T-cell responses have been shown to be evident in HCV patients with resolved infection, while diminished in patients with chronic hepatitis C." (PMID 25215259, 2014). "In summary, CD28 is crucial for protection against N. brasiliensis secondary infection and plays a key role in the recruitment of TFH cells, memory CD4+ T cells and follicular B cells." (PMID 24516382, 2014). "Reducing the proportion of CD4 in DRM in macrophages using CD4P-, CD4R- or CD4P-R- mutants, in all cases led to a decrease in infection as observed using three different HIV-1 assays." (PMID 24465876, 2014). "VCP has previously been shown to play a role in Vpu-dependent CD4 degradation, but it is likely to impact the VSV-G pseudotyped HIV single-cycle infection used here through a separate mechanism." (PMID 24817247, 2014). "In a parallel to the finding in mice, children with CMV who have few CD4+ T cells have prolonged shedding of CMV in the salivary glands, and dysfunctional CD4+ T cells have been reported during primary infection." (PMID 24872114, 2014). "This antigen presenting cell type picks up vial antigen in the IAV-infected lungs, migrate from the lungs into the dLN late in the infection cycle (i.e. between 6 and 12 d.p.i.)where these cells facilitate TFH differentiation of Ag-activated CD4+ T cells." (PMID 25251568, 2014). "For example, ESAT-6 and Ag85B represent major antigenic targets for CD4+ and CD8+ T cells and are actively expressed during overt infection." (PMID 24804000, 2014). "The differences in outcomes among the options were reduced, especially in terms of infant infection and ART initiation of women with CD4 cell count of ≤350 cells/mm3." (PMID 24604067, 2014). "In conclusion, we present an infection model that allows the analysis of the MAP induced stimulation and pro-inflammatory activity of CD4+ T cells." (PMID 24728142, 2014). "We here identify increased Nedd4 protein levels in both CD4+ and CD8+ T cells following SHIVSF162P3-infection of naïve macaques." (PMID 24614057, 2014). "We investigated the alteration of CRP, WBC, neutrophil count, suPAR levels, CD4+ CD25high Tregs, CD64+ and CD177+ neutrophils and monocytes in 12 acute ischemic stroke patients free of infection within 6 hours and one week after the insult." (PMID 24597828, 2014). "In contrast, resistant C57BL/6 mice eliminate the virus from the CNS by specific cellular immunity, including effective CD4+ and CD8+ T cell responses during the acute infection phase." (PMID 25391297, 2014). "Previous studies have demonstrated that both CD4+ T cells and CD8+ T cells are required for elimination of HBV from the liver during natural infection." (PMID 25526800, 2014). "While CD4+ helper T cells support the generation of antibody and CD8+ T-cell responses in lymphoid tissues, both CD4+ and CD8+ T-cells also contribute directly to pathogen control at sites of infection." (PMID 25121482, 2014). "CD4+ T cells are the major target for HIV and massive depletion of CD4+ T cells results during acute infection in adults, with ongoing preferential infection of activated and HIV-specific CD4 T cells in chronic infection." (PMID 25161656, 2014). "The ability to evaluate infectivity across a broad spectrum of CD4 and CCR5 expression levels underscores the innate inter-dependence of CD4 and CCR5 levels in the context of infection." (PMID 24957778, 2014). "Carnitines have been shown to support immune function, supporting the production of CD4+ and CD8+ T cells during infection." (PMID 24763072, 2014). "Further, the treatment of macrophages with chloroquine prior to BCG-dHCM infection, inhibited IFN-γ production by memory type CD4+ T cells." (PMID 24690183, 2014).
infection (continued). "In our viral model, the initial response to infection up-regulated mRNAs that seemed related to a T-dependent response, including CD3, CD8αβ, and CD4 genes." (PMID 25338079, 2014). "Here we demonstrated that VNPs have decreased infection of both stem cell memory and central memory CD4+ T cells by HIV, and also had increased frequencies of Ki-67+ CD4+ T cells." (PMID 25167059, 2014). "Increased numbers of CD4+ and CD8+ naïve (CD4+CD44lowCD62Lhigh and CD8+CD44lowCD62Lhigh, respectively) as well as CD4+ and CD8+ memory/effector (CD4+CD44highCD62Llow and CD8+CD44highCD62Llow) T cells were detected at weeks 2 and 8 after infection." (PMID 25411790, 2014). "HSV-specific memory T cells representing both CD4+ and CD8+ subsets were readily detected in the vagina/cervix of HSV-2-infected guinea pigs at 2-6 months post infection." (PMID 25485971, 2014). "Markers of infection by HIV-1, such as CD4+ T-cells, CD8+ T-cells, and HIV-1 RNA, showed satisfactory medians in the treated groups." (PMID 24719500, 2014). "There are many subsets of CD4+ T cells, such as T-helper 1 (Th1), Th2, Th17, and regulatory T cells (Tregs), and all these subsets co-operate or interfere with each other to control infection; the dominant subset may differ between active and latent Mtb infection cases." (PMID 24795723, 2014). "CpG pre-conditioning also decreased the percentage of CD45+CD4+CD3+CD25+FoxP3+ regulatory T cells in spleen and brain 42 h after infection." (PMID 24456653, 2014). "In accordance with the results of HIV-1NL4-3 infection, CCR5-tropic HIV-1YU2 strain was also capable of inducing Nec-1-sensitive necroptosis in primary CD4+ T cells." (PMID 24714696, 2014). "Increased Nedd4 protein levels were noted in both CD4+ and CD8+ T cells following SHIVSF162P3-infection of naïve macaques." (PMID 24614057, 2014). "These cells also express CD4 and both co-receptors CXCR4 and CCR5, which permits infection by both T- and M-tropic viruses." (PMID 24820173, 2014). "We show that the early immune response to primary low dose L. major infection is dominated by CD8+ T cells while high dose infection preferentially induced proliferation and IFN-γ production by CD4+ T cells." (PMID 25412267, 2014). "In our model, T cell activation was measured by assessing frequency of CD44HI cells within CD4+, CD8+, and CD8+Thy1.1+ T cells at day 5 (peak of the antigen-specific CD8+ T cell response) and day 14 following resolution of infection." (PMID 24796533, 2014). "IFNγ producing CD4 and CD8 T cells were detected at a higher frequency and much earlier during secondary infection as compared to primary infection in the same chimpanzees." (PMID 24982656, 2014). "A different study revealed that the percentages of CD4+ and CD8+ T cells were significantly decreased for a few days shortly after PRRSV infection, but returned to pre-infection levels on days 8–10 post-inoculation." (PMID 24465897, 2014). "To determine this, we assessed CD4+ and DN T cells response in the dLNs and spleens of infected mice C57BL/6 mice at different times after infection corresponding to early, peak and resolution of lesion progression." (PMID 25233487, 2014). "Of note, the absolute number of CD4+ T cells that are infected TCM in VNPs compared to PPs loses significance, but maintains a trends towards decreased infection (p = 0.0999)." (PMID 25167059, 2014). "The PG9/PG16 (N160K) and VRC01 (N279/280A) resistance mutations reduce the efficiency of entry; both requiring higher levels of CD4 and CCR5 to achieve similar levels of infection as their wt counterparts." (PMID 24957778, 2014). "HIV-R3A infection leads to rapid immunopathogenesis including depletion of human total leukocytes and CD8 T cells, as well as CD4 T cells." (PMID 25077616, 2014).
infection (continued). "CD4+ and CD8+ T cells-depleted mice, which still had DN T cells, retained some level of infection-induced resistance as evidenced by significantly (p<0.01) lower parasite burden compared to naïve mice (primary infection)." (PMID 25233487, 2014). "Hence, a preexisting CD4+ T-cell pool directed towards commonly conserved epitopes due to previous infections by human IAVs (H1N1 1918–1976, seasonal H1N1 1977–2009, pandemic H1N1 2009–2013, H2N2 1957–1968, and H3N2 1968–2013) - could potentially provide cross-immune protection to the H7N9 virus." (PMID 24609014, 2014). "Thus, mucosal CD4+ T-cells may be responsible for maintaining peak viral loads in depleted RMs similar to that in controls, before being severely depleted in the first weeks of infection due to the high levels of SIV replication." (PMID 25356757, 2014). "Both infections target macrophages and dendritic cells; HIV targets CD4 cells directly while Leishmania does this indirectly by promoting HIV replication in CD4 cells that play a pivotal role in the immune response needed to combat both infections." (PMID 25412435, 2014). "Subjects with silent infections had significantly higher numbers of CD3+ cells (median: 1523.0/mm3), CD4+ cells (median: 687.0/mm3), and CD8+ cells (median: 677.5/mm3)." (PMID 24646014, 2014). "While Jurkat T cells provide a reliable model in which to evaluate inhibition, we wished to confirm our data using primary CD4+ T cells, which are the main cell type infected by HIV-1 during natural infection." (PMID 25700025, 2014). "Frequencies of peripheral CD20+ B cells, CD4+ T cells and CD8+ T cells rapidly decreased, reaching nadir levels by about day 4 post-infection in the animals that ultimately required euthanasia." (PMID 25412185, 2014). "Key aspects in this regulation, however, particularly those pertaining to the infection status of APCs and the role of distinct APC subtypes in driving CD4+ versus CD8+ TEFF-cell responses, remain poorly understood." (PMID 25121482, 2014). "In the four animals that survived, frequencies of CD20+ B cells, CD4+ T cells and CD8+ T cells also declined but to a lesser extent and in two of the animals recovered to pre-infection levels days 10–14 post-infection." (PMID 25412185, 2014). "Consistent with an involvement of MHC-II-expressing APCs in driving CD4+ TEFF-cell responses, MHC-IIhi cells accumulated in the skin during the first week post-infection." (PMID 25121482, 2014). "Further, we analyzed CD4+ T cell SIV DNA turnover early during infection compared to during chronic infection, and found higher levels of turnover of SIV DNA in resting CD4 T cells during early SIV infection." (PMID 24710023, 2014). "On infection with C. rodentium, Lgals1−/− mice showed a significant decrease in the number of CD3+, CD4+ and CD8+ T cells compared to uninfected control mice at day 15 p.i.." (PMID 25243744, 2014). "Such chronically infected mice were then reconstituted with CD4+ and CD8+ T cells 28 days after infection." (PMID 24728142, 2014). "The numbers of CD86+ CD4+ and CD8+ T cells increased during the course of infection, with maximal numbers around day 10 p.i.." (PMID 25144228, 2014). "Studies using flow cytometry suggested that there was a progressive increase in both CD3+ CD4+ and CD3+ CD8+ cells in the first week of infection." (PMID 24473125, 2014). "In particular, lower proviral DNA values in MHC class IA M4 macaques and lower CD4+T cell counts in MHC class IA, IB, and class II M4 animals were detected during the acute and chronic (24–46 weeks) phases of infection, respectively." (PMID 24695530, 2014). "Previous studies found that total CD3+ T cells and total CD4+ T cells were decreased in SFTSV-infected patients, more so during acute phase infection, in severe cases, and in those who eventually die from the disease." (PMID 24658451, 2014).
infection (continued). "IL-9-GFP detection in CD4+ T cells in the lung peaked early and declined during the course of infection, whilst IL-9-GFP+ ILC2s were detectable early and remained present throughout, suggesting a transient window of CD4+-T-cell-derived IL-9 in this model." (PMID 24586147, 2014). "These stages of thymyocyte development were analysed by enumeration of CD4 SP, CD8 SP, DN and DP cells at day 14 post infection." (PMID 23554993, 2013). "On average, IL-7 25 ng/mL increased the number of HIV-1-infected CD4+ (CD8− p24gag+) T cells in HIV-1LAI.04- and HIV-1BaL-infected lymphoid tissues 4.1±0.4 fold and 7.7±1.8 fold, respectively, on day 9 post infection (n = 8 and 6, p<0.001)." (PMID 23408885, 2013). "During the testing of a therapeutic DNA vaccine encoding the TSA-1 antigen of T. cruzi in a murine model, the immunized mice exhibited significant increases in CD4 and CD8 T cells producing IFN-γ during the chronic phase of infection." (PMID 23497041, 2013). "The vast majority of PD-1+ CD4 and CD8 T cells were of the memory phenotype (94.6%±0.9 and 91.9%±1.3, respectively) prior to as well as after infection." (PMID 23555918, 2013). "However, in this study, although primary DC were used (defined as BDCA-1+ and BDCA-4+ cells), total DC were present at a frequency of only 0.89% and therefore the frequency of mDC may have been too low to demonstrate an effect of mDC on the infection of resting CD4+ T cells." (PMID 24339779, 2013). "Infected macrophages secrete cytokines such as Tumor Necrosis Factor- (TNF-) to recruit immune cells (mainly, CD4+ and CD8+ T cells) to the site of infection and prime the activation of effector functions in these cells." (PMID 23580062, 2013). "In humanized mice transplanted with either CD4+ T cells or CD34+ HSC, ZFN-mediated CCR5 disruption has been shown to confer resistance to de novo infection by CCR5-tropic HIV-1, thereby controlling virus replication." (PMID 24086129, 2013). "How CD4+ T cells provide help to CD8+ T cells – during priming, memory and/or mobilizing to the site of infection – remains a pending question, which will require further analysis." (PMID 24068938, 2013). "Frequent, repeated HIV screening can shorten the period from infection to diagnosis, as seen in our HIV-infected repeat testers who had higher CD4 counts than the first time testers, and offers the hope of preventing disease progression and mortality." (PMID 23626808, 2013). "From 15 days post-infection onwards, T cell responses in the LNs decreased and we could not detect any CD4+ Granzyme B+ T cell subset, showing that the induction of Granzyme B-expressing CD4+ T cells correlates with the triggering of CD4+ and CD8+ T cell responses." (PMID 24367519, 2013). "Competitions in U87.CD4.CCR5 using independently generated and titered viral stocks not only recapitulated outcomes from PBMC dual-infections, but did so in a shorter amount of time and at a lower MOI." (PMID 23638182, 2013). "Neutrophils, CD4, and CD8 T-cells peaked early during infection (day 14) and then rapidly decreased in numbers in both the BALF and single cell suspensions of the lungs (day 21), paralleling the reduction of CP titers." (PMID 24204830, 2013). "While multiple reports have described CD4-independent SIV and HIV generated in various model systems, strict CD4 dependence is a general rule for viruses in vivo during normal infection." (PMID 24219995, 2013). "Enumeration of cell infiltrates showed that total cell numbers, and CD4+ and CD8+ T cell numbers in TLR2KO mice were similar to WT at 7 weeks following infection, a time when the percentage of Treg cells was lower in TLR2KO." (PMID 23785280, 2013). "Our data have also demonstrated that in pulmonary PCM, early NO production inhibits the activation and migration of CD4+ and CD8+ T cells to the site of infection." (PMID 23936574, 2013).